GSK3B (glycogen synthase kinase 3 beta)
Diseases named in the same sentence as GSK3B in open-access papers (continued):
Sharing a sentence is not in itself a finding about the gene and the disease.
tumor (continued). "PI also inhibits tumor angiogenesis through multiple pathways and targets, as well as inhibiting the epithelial-mesenchymal transition (EMT) of tumor cells by suppressing the CCR10-mediated PI3K/Akt/GSK-3β/Snail signaling pathway." (PMID 36429033, 2022). "These modifications have also been associated with tumor progression together with PML ubiquitination and phosphorylation at S402 and S518, and CAP1 phosphorylation by GSK3B at T307, S308 and S31034–37." (PMID 35292711, 2022). "Subcutaneous application was the best way to deliver UM + LunLip to tumor cells; it resulted in the smallest tumor volume, higher expression of Caspase-3, and lower expression of GSK-3β and Ki-67." (PMID 36297649, 2022). "GSK3-β is expressed at higher levels in tumour cells and metastatic lesions compared to normal tissue." (PMID 36430630, 2022). "Further investigation has revealed that CB can powerfully reverse EBV-miR-BART22-induced cisplatin resistance via upregulating MAP2K4 to antagonize Myh9/GSK3β/β-catenin and its downstream tumor stemness and EMT signals in nasopharyngeal carcinoma." (PMID 36237327, 2022). "Other PDAC GSK3β inhibitory treatments revolve around synergistic pharmacological interaction with Gemcitabine to treat tumour stages ranging from preclinical models to refractory, to advanced or metastatic." (PMID 36430630, 2022). "The Wnt signaling pathway is a major mechanism in tumor biology, and the activation of this pathway involves various processes such as Wnt2, β-catenin, GSK3β, and Axin." (PMID 36861110, 2022). "Deregulated GSK3β also takes part in tumor cell survival, resistance of apoptosis, proliferation, migration and invasion, as well as sustaining cancer stemness." (PMID 35281088, 2022). "Given that GSK3β inhibition increases NOTCH1 signaling and CLL cell survival, and NOTCH1 signaling is oncogenic in CLL, we suggest that GSK3β has a tumor suppressor role in CLL." (PMID 36050315, 2022). "Given the important role of GSK-3β in cyclin D1 degradation, GSK-3β has a tumor suppressor function in HepG2215 cells." (PMID 35722140, 2022). "We first investigated the upregulated four genes (BDNF, PTGS2, CTNNB1, and GSK3B) in the tumor sample expression profile in CC patient tissue using RNAseq data." (PMID 35054980, 2022). "This evidence indicated that NBT inhibited xenograft tumor development in vivo by suppressing p-GSK3β/β-catenin/Cyclin D1 signaling." (PMID 36263164, 2022). "PTK6-T2 blocked the binding between FSCN1 and the pre-mRNA of PTK6, and thus reversed the promotion effect of FSCN1 on ESCC tumor progression via the AKT/GSK3β signaling pathway." (PMID 35401239, 2022). "The Akt/GSK-3β signaling is a widely-known indispensable controller in different biological processes of the multifarious types of tumor cells." (PMID 35112982, 2022). "MYH9 was an effective promoter of tumor stemness, which degraded GSK3B and β-catenin destruction complex by ubiquitin-mediated process to induce the downstream tumor stemness phenotype." (PMID 35242279, 2022). "Some studies showed that GSK-3β acted as a tumor suppressor gene in HCC and negatively regulated Wnt/β-catenin." (PMID 35722140, 2022). "In off state of canonical Wnt signaling pathways, β-catenin is mainly expressed at the cytoplasm, and Gsk-3β inhibits tumor growth by degrading β-catenin." (PMID 35433476, 2022). "In this regard, Il-1β activates the Wnt signaling pathway directly by inactivating GSK3β, resulting in increased β-catenin levels and promoting Wnt signaling during tumor development." (PMID 35511336, 2022). "This is likely because, GSK-3β phosphorylates PD-L1 in tumor cells to induce its degradation, and GSK-3β inactivation can be seen in some cancers to stabilize PD-L1 expression." (PMID 35911672, 2022). "Expression status of GSK3B is positively correlated with tumor progression in multiple human malignancies." (PMID 36468011, 2022).
tumor (continued). "Aberrant GSK-3β activity is relevant to multiple tumor-related diseases, and it is prominent as a potential therapeutic target 17-18." (PMID 36263164, 2022). "Since the Wnt-GSK-3β signaling pathway is well known for its tumor-related function, GSK-3 and ABLIM1 probably interact with malignancies." (PMID 36583064, 2022). "Subsequently, we examined the protein levels of EMT markers and GSK-3β/β-catenin/ZEB1 pathway in nude mice tumor tissue." (PMID 36386155, 2022). "GSK3β is involved in tumor formation and progression and has been suggested as a tumor suppressor because its activation accelerates the degradation of oncogenes such as β-catenin, cyclin D1, and c-Myc." (PMID 35606353, 2022). "On the one hand, GSK3β has been recognized as a tumor suppressor because it downregulates many proto-oncoproteins and cell cycle checkpoint proteins, thereby inhibiting cell proliferation." (PMID 35606353, 2022). "In a mouse model of CAC, Ya-Chun Chou demonstrated that Boswellia serrata mediated Akt/GSK3β/cyclin D1 signaling pathway and altered the composition of gut microbiota to alleviate tumor growth." (PMID 35733095, 2022). "NDRG2 inhibits cell signaling, such as AKT-, NF-κB-, STAT3-, and TGF-β-mediated signaling, to induce tumor metastasis, and induces activation of GSK-3β which has anti-tumor effects." (PMID 36012631, 2022). "Our previous study has revealed that PGC-1α functions as a tumor promoter through the activation of AKT/GSK-3β/β-catenin signaling." (PMID 36612155, 2022). "GSK-3β blockade downregulates the NF-κB pathway, modulates immune cell PD-1 and tumor cell PD-L1 expression, and increases CD8 + T cell and NK cell function." (PMID 35815408, 2022). "IF staining of the tumor tissues demonstrated that the expressions of PD-L1 and phospho-GSK3β/S9 were decreased when eEF2K was knocked down, supporting that eEF2K modulated T cell activity by regulating PD-L1 expression in mouse model." (PMID 35347072, 2022). "In a xenograft mouse model of human WM, Enzastaurin significantly inhibited Akt and GSK3β phosphorylation in tumor cells and inhibited the growth of tumor WM cells in a SCID subcutaneous tumor model." (PMID 36232447, 2022). "In contrast, the inhibition of glycogen synthase kinase-3β (GSK-3β) can suppress tumor growth at the same level as the anti-PD-1 drug." (PMID 36297649, 2022). "Our study showed a slight increase of GSK3β phosphorylation, which inhibits GSK3β activity as a kinase and decreased the phosphorylation of its targeted protein, β-catenin, in the tumor of vimentin null mice." (PMID 35399505, 2022). "In a previous study, EBV-miR-BART22 was found to activate the PI3K/AKT and GSK3β/β-catenin pathways and their downstream tumor stemness and EMT signals." (PMID 35907914, 2022). "Elraglusib is the first GSK-3β inhibitor to demonstrate single-agent clinical activity in patients with refractory tumours." (PMID 36104795, 2022). "The PI3K/AKT/GSK3β/Snail signaling has previously been shown to be critical to tumor metastasis via the modulation of EMT induction in multiple cancers." (PMID 35574325, 2022). "Regulating Akt/GSK3β/Snail signal transduction axis can inhibit tumour cell EMT and chemoresistance." (PMID 35426224, 2022). "A previous study demonstrated that the total protein level of GSK-3β was much lower in HCC tumor tissues than in adjacent liver tissues." (PMID 35581180, 2022). "In a 7,12-dimethylbenz[a]anthracene (DMBA)-induced animal tumor model, fucoidan suppresses breast cancer cell-xenografted tumor growth by inhibiting PI3K/AKT/GSK3β signaling." (PMID 35624775, 2022). "In some cases, GSK-3β not only has tumor suppressor function, but it also has tumor promoter function." (PMID 35722140, 2022).
tumor (continued). "The reported tumor suppressor function of GSK3β involves phosphorylation of the hinge and ligand binding regions of AR, resulting in decreased activation of AR gene targets and inhibition of cell proliferation." (PMID 35402240, 2022). "By inhibiting GSK-3β we can provide a therapeutic approach to controlling autophagy induction by manipulation of the LKB1-AMPK pathway to selectively treat tumours or metastatic lesions." (PMID 36430630, 2022). "GSK-3β has multiple roles in tumour progression including the modulation of oncogenes, cell cycle regulators and mediators of epithelial–mesenchymal transition." (PMID 36104795, 2022). "Here, the tumor suppressor GSK3β phosphorylates HIF-1α at three serine residues within the human HIF-1α N-terminal transactivation domain, which results in the Fbw7 and USP28-mediated HIF-1α ubiquitination and VHL-independent proteasomal degradation." (PMID 36699028, 2022). "EBV encoding miR-BART22 enhances DDP chemoresistance by targeting MAP2K4 and activating MYH9/GSK3β/β-catenin-mediated tumor stemness pathways." (PMID 35105963, 2022). "For many years, the role of GSK-3β in cancer cells as a pro-oncogenic or tumour-suppressor protein has been a much-disputed topic, which has stunted therapeutic targeting of this kinase." (PMID 36430630, 2022). "Our present data revealed that PPP1R14C, together with PRKCI, and PP1, maintained the phosphorylation of GSK3β at Ser9, which accelerated tumour proliferation and metastasis in TNBC." (PMID 35090098, 2022). "Although GSK3β plays a key role in regulating Wnt/ β-catenin signalling activity, its role in other oncogenic or tumour suppressor pathways is less well understood." (PMID 34739494, 2021). "Meanwhile, the levels of Ki-67, Slug, p-PI3K (Tyr458), p-AKT (Ser473) and p-GSK3β (Ser9) were elevated in tumor tissues." (PMID 34595179, 2021). "GSK-3β negatively regulates the cell surface expression of LAG-3 on tumor infiltrating T lymphocytes." (PMID 34356465, 2021). "To address the relationship of GSK3β with tumor metastasis, we tested the effects of small-molecular GSK3β inhibitors, AR-A014418 and SB-216763, on MG-63 cell migration and invasion." (PMID 33969873, 2021). "Given the pleiotropic nature of GSK-3β, the net effect of GSK-3β perturbance on tumor development is likely context dependent." (PMID 34356465, 2021). "More importantly, MSJZD augmented the E-cadherin level and weakened the Vimentin, Snail, TGF-β1, p-AKT, and p-GSK3β levels in A549 tumor-bearing nude mice, which was consistent with in vitro experiments." (PMID 35111070, 2021). "Nonetheless, dual roles of GSK-3β in tumor development have been revealed to incur apoptosis and enhance proliferation in multiple diseases." (PMID 34555811, 2021). "To verify the AD pathological changes that are mediated by PD1, we chose GSK3β as the downstream target of PD1/PDL1 because the PDL1/GSK3β complex exists in tumor cells and the brain." (PMID 34977020, 2021). "Consistently, there was a significant decrease in BRCA1 protein level and increase in γ-H2AX level in the GSK3β KO tumor xenografts treated with simmiparib." (PMID 33589588, 2021). "Collectively, these data demonstrate a key role for the GSK-3β isoform in controlling T cell mediated anti-tumor immunity." (PMID 34142056, 2021). "The AKT/GSK-3β signaling pathway is one of the main survival pathways of tumor cells with abnormally high activation in many malignant tumors; specifically, its dysregulation is closely related to the occurrence, migration, and invasion of malignant tumors." (PMID 34966427, 2021). "SIRT7 underpins the anti-tumor effect of intermittent fasting (IF) by enhancing the effects of fasting on GSK3β activity and AMPK signaling." (PMID 34433808, 2021). "Studies have shown that GSK3B can inhibit the wnt/β-catenin pathway and thereby inhibit tumor metastasis." (PMID 33782407, 2021).
tumor (continued). "It should be noted that there was an overall prolonged survival of the Gsk3b cKO mice of 5–10 days compared to all other strains, with tumor growth being slower in these mice." (PMID 34142056, 2021). "Aberrant Wnt/β-catenin signaling is involved in the progression of different tumor types through modulation of downstream targets, such as c-myc, cyclin D1, and GSK-3β." (PMID 34090445, 2021). "Taken together, the immunomodulatory effects of GSK-3β inhibition go beyond the regulation of immune checkpoints to the direct enhancement of anti-tumor T cell mediated cytotoxicity." (PMID 34356465, 2021). "Overall, we demonstrate that WSX1 is a tumor suppressor that reinforces hepatic immune surveillance by blocking the PI3Kδ/AKT/GSK3β/PD-L1 pathway." (PMID 34108491, 2021). "Taken together, these data demonstrate a clear difference in T cell distribution in response to the presence of tumor growth with a higher level of tumor-infiltrating T cells being seen in the Gsk3b cKO mice." (PMID 34142056, 2021). "It has been reported that SSE inhibits tumor growth by regulating GSK3β/β-catenin and its upstream AKT and ERK signals." (PMID 33790787, 2021). "The potentiation of synthase kinase GSK3β by O-GlcNAcylation will promote changes in metabolism in tumors and cells in the tumor microenvironment." (PMID 34588426, 2021). "Due to its ability to phosphorylate and thereby target some pro-oncogenic molecules for ubiquitin-dependent proteosomal degradation, GSK3B has been thought of potential tumor suppressor in some cancers." (PMID 35096583, 2021). "This relationship was more evident in cases with strong GSK-3β expression or the expression in > 50% of the tumor." (PMID 33767989, 2021). "Our findings indicated that the expression of GSK3β is significantly lower in eHCC tumor samples in comparison to normal samples in blood." (PMID 34659334, 2021). "Considering these interactions with components of tumor growth pathways, GSK-3β has become a critical molecule to be used in the fight against cancer and the development of new drugs." (PMID 33767989, 2021). "Multiple findings indicated that saponins compounds derived from TTM possess potential properties of anti-inflammation and anti-tumor mediated by GSK-3β signals." (PMID 34955834, 2021). "This suggests that there is an increase in the cells migrating to the tumor site within Gsk3b cKO mice and that they efficiently infiltrate any tumors and contribute to controlling disease progression." (PMID 34142056, 2021). "In this study, we showed that GSK3β acts as a tumour suppressor gene; m6A‐modifed GSK3β was recognized and degraded by YTHDF2, leading to the activation of Wnt/β‐catenin signalling and further promoting the proliferation of CRC cells in vitro and in vivo." (PMID 34709763, 2021). "Len-sh-circ_PVT1 promotedhe texpression of DKK1, NKD1, and p-GSK3β and inhibited wnt4 and β-catenin in tumor." (PMID 34336825, 2021). "Pharmacological blockade using A438079 (10 μM) and AZD9056 (10 μM) or transfecting CRC cell lines with P2X7R siRNA reduced CRC proliferation by inhibiting P13/Akt/GSK-3-β/β-catenin pathway which is an important signaling pathway in tumor development." (PMID 34987401, 2021). "This is consistent with our finding that GSK3β acts as a tumor suppressor, especially in the earlier stage of tumorigenesis, by stabilizing SIRT7 to suppress AKT activation." (PMID 34433808, 2021). "GSK3β acts as a molecular regulation switch while the role of its activation in tumor progression still remains a controversy." (PMID 34329303, 2021). "In breast and tumor tissues, delphinidin treatment also inhibits the expression of β-catenin, p-GSK-3β, c-Myc, cyclin-D1, and MMP-7 and upregulates miR-34a, a master regulator of tumor suppression." (PMID 33540611, 2021). "Some potential drugs targeting the PD-L1 regulators, such as IFN-γ, MAPK, and GSK3β exhibited remarkable synergistic anti-tumor effect with ICIs." (PMID 34088360, 2021).
tumor (continued). "Further, phosphorylation of AKT and GSK3β was higher in AL tumors compared with TRF tumor tissue in the OVX mice, suggesting that TRF is able to attenuate tumor growth by modulating the AKT pathway." (PMID 33495474, 2021). "In the context of tumour development, GSK3β has been shown to play both oncogenic and tumour suppressor roles, depending upon tissue, signalling environment or disease progression." (PMID 34739494, 2021). "GSK3β has been reported to promote degradation of PD-L1 via phosphorylation at extracellular T180 and S184, contributing to anti-tumor immunity." (PMID 33879767, 2021). "9-ING-41 is also a potent, selective small molecule inhibitor of GSK-3β, which has demonstrated anti-tumor activity in patient-derived xenograft mice (PDX) of various human cancers including PDAC." (PMID 34356465, 2021). "Historically, GSK3β has been thought of as a potential tumor suppressor due to its regulatory effect in the Wnt/β-catenin pathway." (PMID 33589588, 2021). "GSK3β inhibition in vivo resulted in a higher tumor burden which was dependent on PD-1 inhibitory pathways, and PD-1 blocking antibodies restored anti-tumor responses." (PMID 34639141, 2021). "Meanwhile, ALDOC positively regulates the Wnt pathway, which is involved in tumor development, by blocking the GSK-3β-axin interaction and targeting axin to a Dvl-induced signalosome." (PMID 34838074, 2021). "The pro-oncogenic activity of GSK3β is based on the findings that deregulated GSK3β maintains tumor cell survival, proliferation, and invasion by enhancing machinery for cell motility and migration." (PMID 34064046, 2021). "GSK3β can display both pro-oncogenic and tumor-suppressive effects as it has diverse roles in numerous cellular processes that also differ among different cell types." (PMID 34064046, 2021). "GSK3β is a tumor suppressor gene, the activation of which inhibits the growth and proliferation of cancer cells through PI3K/Akt signaling." (PMID 34208283, 2021). "The inhibition of GSK3b reduces self-renewal potential, tumour sphere formation and the mRNA expression of the stem cell markers Sox2, Oct4, and Nanog leading to the induction of cell differentiation." (PMID 34831291, 2021). "This tumor-growth inhibitory effect of 3-HAA was at least partially attributed to its inhibition of stemness of HCC cells via suppressing AKT/GSK-3β/β-catenin signaling." (PMID 34230478, 2021). "During gastrin-induced migration, Fas-induced EMT and endothelin-1-mediated EMT and tumour invasion, the inactivation of GSK-3β by PI3k/Akt signalling promotes Snail expression and β-catenin stabilisation." (PMID 33239678, 2021). "We further verified the expression levels of YTHDF2, GSK3β, β‐catenin and Cyclin D1 in 150 pairs of tumour and ANTs." (PMID 34709763, 2021). "And DUXAP9 involved with activity of PI3K/Akt/GSK3β/Snail pathway in ccRCC tumor tissues need further verification." (PMID 34168980, 2021). "At all supplement concentrations, mice receiving the combination treatment exhibited the highest levels of GSK-3β and lowest levels of p-S552-β-catenin and p-S33-37-Y41-β-catenin in tumor tissues." (PMID 33805447, 2021). "As PARP inhibitors are a topic of great interest in PDAC, further studies are warranted to elucidate the complex interactions at the crossroads of GSK-3β, DNA damage response, and anti-tumor immunity." (PMID 34356465, 2021). "As a tumor suppressor, GSK3β can phosphorylate and inactivate several oncogenes, including β-catenin, c-Myc, and cyclin D1 – ultimately inhibiting tumor cell proliferation." (PMID 34023818, 2021). "The present results show that the combination treatment of Avastin with FO and Se significantly increased the expression of GSK3β and decreased β-catenin in tumor tissues." (PMID 33805447, 2021). "Recently, an elegant study demonstrated that the combination of fasting and metformin impairs tumor growth by boosting GSK3β activity." (PMID 34433808, 2021).